HMGA1 (high mobility group AT-hook 1)
Diseases named in the same sentence as HMGA1 in open-access papers (continued):
Sharing a sentence is not in itself a finding about the gene and the disease.
diabetes (16 papers, 2008 to 2023). "HMGA1 deficiency causes insulin resistance and diabetes through impairing the transcription of the insulin receptor gene INSR and of the insulin-like growth factor binding protein-1 (IGFBP-1) genes." (PMID 31963852, 2020). "It has been demonstrated that HMGA1 is associated to both the risk for diabetes and the risk of developing cardiovascular complications." (PMID 30674322, 2019). "We have previously demonstrated that loss of function in HMGA1 in both human and mice compromised pancreatic endocrine function and resulted in diabetes." (PMID 25628604, 2014). "Altogether, these results strongly suggest that HMGA1 deficiencies may contribute to the development of specific forms of diabetes mellitus." (PMID 31963852, 2020). "In addition, a specific variant of HMGA-1 has been found to increase the risk for diabetes, coronary artery disease, and acute myocardial infarction." (PMID 30486335, 2018). "We sought to investigate the HMGA1-diabetes association and to characterize IVS5-13insC allele frequencies and linkage disequilibrium (LD) in 3,070 Caucasian, Hispanic, and African American patients from the INternational VErapamil SR-Trandolapril STudy (INVEST)." (PMID 23302499, 2013). "More recently, we showed that loss of HMGA1 expression, induced in mice by disrupting the HMGA1 gene, caused a type 2-like diabetic phenotype, in which, however, impaired glucose tolerance and overt diabetes coexisted with a condition of peripheral insulin hypersensitivity." (PMID 19460132, 2009). "This is particularly interesting, as both HMGA1 and miR-218 are involved in the development of cardiovascular complications in diabetes." (PMID 33639953, 2021). "High-mobility group AT-hook 1 (HMGA1) is a key partaker in cardiovascular complications of diabetes, both at the vascular and the cardiac level." (PMID 33639953, 2021). "We used logistic regression to test association of the HMGA1 IVS5-13insC and diabetes, adjusted for age, gender, body mass index, and percentage European, African, and Native American ancestry." (PMID 23302499, 2013). "Although the relevance of our data to the clinical setting requires further investigation, they provide compelling evidence for the identification of HMGA1 as a novel nuclear activator of FoxO1 gene transcription, which may help explaining noted differences in diabetes phenotypes." (PMID 29052178, 2018). "Using brilliant databases and bioinformatics tools, we identified GABBR1-centered ceRNAs formed by PDGFRB and WNT2B via hsa-miR-19-3p and RNA-RNA interactions with HMGA1 and SMARCA4 as shared molecules between diabetes and viral infection." (PMID 37969011, 2023). "On the basis of these results, we achieved a shared interRNA mechanism between diabetes and viral infections, which consisted of GABBR1, HMGA1, and SMARCA4." (PMID 37969011, 2023). "Mice were subjected to STZ injection to establish a diabetes model and then subjected to AAV9-HMGA1 injection to overexpress HMGA1." (PMID 32123163, 2020). "Although the current study suggests the lack of a functional role for IVS5-13insC, further study of HMGA1 is warranted to clarify the role of this gene in diabetes pathogenesis." (PMID 23302499, 2013). "Future studies on the interplays among HMGA1, PDX-1, and MafA might be useful in understanding the molecular basis of clinical phenotypes in certain clinical conditions where insulin secretion becomes compromised (i.e., diabetes mellitus and other categories of glucose intolerance)." (PMID 25628604, 2014).
prostate carcinoma (16 papers, 2003 to 2025). A carcinoma that arises from epithelial cells of the prostate gland. "Increased levels of HMGA1 were shown to be correlated with the development of high-grade tumors in various cancer types and more recently it was demonstrated that overexpression of HMGA1 is also associated with late stage prostate cancer." (PMID 23798998, 2013). "PCAF also induces acetylation of HMGA1 proteins in PC-3 human prostate cancer cells and acetylates HMGB1, which in turn regulates the release of HMGB1 and is linked to the cellular inflammatory response." (PMID 39554048, 2025). "NAT10 can mediate prostate cancer (PCa) cell proliferation through high mobility group AT‐hook 1 (HMGA1)‐mediated cell cycle alterations." (PMID 39640362, 2024). "Recently, miR-512-5p has been shown to modulate the expression of the apoptosis regulator MCL-1, and miR-296-5p has been demonstrated to reduce cell proliferation of breast and prostate cancer cells by targeting SCRIB or HMGA1, respectively." (PMID 29221158, 2017). "The protein levels of these genes were significantly decreased in prostate cancer cells transfected with miR-195, except for vimentin and HMGA1." (PMID 26337460, 2015). "In a neo-adjuvant study, levels of hsa-miR-765 were increased and HMGA1 expression was almost completely lost in prostate cancer specimens from patients treated with a single dose (250 mg) of fulvestrant 28 days before prostatectomy." (PMID 24837491, 2014). "HMGA1, an oncogenic protein in prostate cancer, was identified as a downstream target of hsa-miR-765 and fulvestrant in cell-based experiments and a clinical study." (PMID 24837491, 2014). "miR-296 downregulated HMGA1 expression in prostate cancer cells, in turn reducing cell proliferation." (PMID 23325049, 2013). "Repression of HMGA1 by miR-296 suppressed invasion of prostate cancer, while expression of K-Ras, a promoter of migration and invasion, was blocked by miR-96 in pancreatic cancer cells and by miR-216 in nasopharyngeal carcinoma." (PMID 23325049, 2013). "To determine the relative level of let-7b and HMGA1 in prostate cancer cell lines we performed qRT-PCR on LNCaP and PC-3 cells." (PMID 23798998, 2013). "The proto-oncogene HMGA1 encodes a chromatin “architectural transcription factor” that, evidence indicates, acts downstream of PIM1 in an HMGA1-mediated prostate cancer induction pathway." (PMID 22912571, 2012). "Further, HMGA1 up-regulates expression of COX-2, and COX-2 over-expression in prostate cancer has been documented and associated with both cancer initiation and progression." (PMID 22912571, 2012). "In prostate cancer cells, miR-195 functions as a tumor suppressor gene by suppressing HMGA1." (PMID 28487599, 2017). "HMGA1 over-expression plays a critical role in carcinogenesis and its up-regulation was observed in many cancer entities like retinoblastoma, pancreatic, colorectal, lung and prostate cancer for example." (PMID 23798998, 2013). "Thus, transcriptional activation of the HMGA1 proto-oncogene promotes prostate cancer progression via pathways that involve both COX2 and PSMA." (PMID 22912571, 2012). "Both c-MYC and HMGA1 have also been found to be over-expressed in prostate cancers, suggesting the importance of the PIM1/c-MYC/HMGA1 signaling cascade in prostate carcinogenesis." (PMID 22912571, 2012). "In prostate cancer (PCa), NAT10 enhances the stability of high mobility group AT-hook 1 (HMGA1) and Keratin 8 (KRT8) by acetylating their mRNAs, hence accelerating cell cycle progression to improve cell proliferation and enhancing EMT progression to facilitate cell migration, respectively." (PMID 41316475, 2025).
bladder cancer (15 papers, 2013 to 2025). "Overexpression of HMGA1 has been associated with the advanced grading, recurrence and poor prognosis of bladder cancer." (PMID 35114891, 2022). "LINC00649, which is located in the cytoplasm of bladder cancer, promotes the progression of bladder cancer by binding to miR-15a-5p to increase the expression of HMGA1 at the posttranscriptional level." (PMID 35864955, 2022). "Up-regulation of let-7i suppressed proliferation and migration of the human bladder cancer cell lines T24 and 5637 by targeting HMGA1." (PMID 31196036, 2019). "In conclusion, let-7i was down-regulated in bladder cancer cells and these in vitro studies showed that up-regulation of let-7i suppressed human bladder cancer cell proliferation and migration by targeting HMGA1." (PMID 31196036, 2019). "Compared to SV-HUC-1, HMGA1 protein was also up-regulated in bladder cancer cell lines T24 and 5637." (PMID 31196036, 2019). "High expression of HMGA1 mRNA was found in bladder cancer cell lines T24 (3.65 ± 0.04) and 5637 (6.22 ± 0.38) as compared to SV-HUC-1 (0.99 ± 0.01, P < 0.001)." (PMID 31196036, 2019). "Transfection of let-7i-5p mimic reduced HMGA1 mRNA and protein expression in bladder cancer cell lines, suggested that HMGA1 as a target gene for let-7i-5p." (PMID 31196036, 2019). "Compared with the SV-40 immortalized human uroepithelial cell line (SV-HUC-1), bladder cancer cell lines T24 and 5637 had low levels of let-7i expression, but high levels of high mobility group protein A1 (HMGA1) expression." (PMID 31196036, 2019). "Our investigation has revealed that cancer stem cell-derived exosomal LUCAT1 enhances the stemness phenotype and chemoresistance of bladder cancer cells by upregulating HMGA1 expression through its interaction with IGF2BP2, thereby contributing to the oncogenicity of bladder cancer." (PMID 40025525, 2025). "Additionally, developing safe and effective interventions targeting the LUCAT1/IGF2BP2/HMGA1 signaling axis to effectively inhibit the stemness transformation of bladder cancer cells and suppress chemotherapy resistance warrants further investigation." (PMID 40025525, 2025). "Moreover, the suppression of the malignant phenotype in bladder cancer (BC) cells induced by LUCAT1 silencing was reversed upon HMGA1 overexpression, highlighting its functional relevance." (PMID 40025525, 2025). "Studies have found that miR-26a suppresses bladder cancer by regulating its target HMGA1." (PMID 36820066, 2023). "In addition, let-7i targets HMGA1 to significantly inhibit the proliferation and migration of T24 and 5637 bladder cancer cells, although let-7i is less expressed in bladder cancer." (PMID 35864955, 2022). "And knockdown of HMGA1 repressed cell proliferation and motility in bladder cancer." (PMID 34090483, 2021). "In addition, Studies have shown that HMGA1 can regulate proliferation and motility of bladder cancer cells." (PMID 31196036, 2019). "Furthermore, to explore how let-7i affects HMGA1 expression in bladder cancer cells." (PMID 31196036, 2019). "However, how let-7i affects HMGA1 gene expression in bladder cancer cells are still unclear." (PMID 31196036, 2019). "In cisplatin-resistant bladder cancer cell lines, FLRT2, HOXC5, SCD, GRM7, HMGA1, ETV7, and SCO2 were highly expressed, while EMP1, SERPINA6, and ZNF124 exhibited lower expression levels." (PMID 39744172, 2025). "Exosome-transmitted LUCAT1 promotes the stemness phenotype and chemoresistance of BC cells via upregulating HMGA1 expression via binding to IGF2BP2, thus contributing to its oncogenic activity in bladder cancer pathogenesis." (PMID 40025525, 2025).
pituitary adenomas (15 papers, 2009 to 2021). "More recently, increased expression of HMGA1 in human pituitary adenomas has also been described." (PMID 25136513, 2014). "Interestingly, HMGA1 overexpression also leads to the development of pituitary adenomas secreting prolactin and GH." (PMID 25136513, 2014). "Interestingly, overexpression of HMGA1 and 2 also has been shown in NETs including small cell carcinomas and pituitary adenomas." (PMID 19156147, 2009). "Moreover, in vitro and in vivo observations have shown that HMGA proteins overexpression has an oncogenic activity, since effectively both HMGA1 and HMGA2 overexpression transforms mouse and rat fibroblasts, and both Hmga1 and Hmga2 transgenic mice develop NK-T cell lymphomas and pituitary adenomas." (PMID 32344629, 2020). "Of note, HMGA1 and HMGA2 are key proteins in the development of pituitary adenomas; indeed, they induce pituitary cell transformation through the enhancement of the activity of E2F1 and other factors." (PMID 34484116, 2021). "Consistent with previous observations, the overexpression of miR-16 reduced both HMGA1 and HMGA2 mRNA and protein levels in the GH3 rat pituitary adenoma cell line." (PMID 31979076, 2020). "In particular, HMGA1P6 and HMGA1P7 expression significantly correlates with HMGA1 mRNA in somatotropic and nonfunctioning pituitary adenomas." (PMID 26895108, 2016). "Finally, HMGA1 transgenic mice develop several benign or malignant neoplasias, such as GH/PRL-secreting pituitary adenomas, T-cell acute lymphoblastic leukemia and T/NK lymphomas." (PMID 26895108, 2016). "Moreover, HMGA1 or HMGA2 overexpression is able to transform mouse and rat fibroblasts, and transgenic mice overexpressing either HMGA1 or HMGA2 develop haematopoietic malignancies and pituitary adenomas." (PMID 24728959, 2014).
Obesity (11 papers, 2015 to 2025). Accumulation of substantial excess body fat. "HMGA1 is overexpressed in adipose tissue, impairs adipogenesis, and prevents diet-induced obesity, and insulin resistance." (PMID 35241739, 2022). "To determine the role of HMGA1 during adipose tissue development and its implications in obesity, we created aP2-HMGA1 mice." (PMID 26411793, 2015). "To evaluate the physiological role of HMGA1 in adipogenesis in vivo and its potential pathophysiological effects during obesity, we created transgenic mice overexpressing HMGA1 in adipose tissue." (PMID 26411793, 2015). "Our results suggest that HMGA1 plays an important function in the regulation of white and brown adipogenesis in vivo and protects against obesity and related metabolic diseases." (PMID 26411793, 2015). "Collectively, these data suggested that HMGA1 overexpression protected transgenic mice from diet-induced obesity, likely due to the decreased adipocyte differentiation capacity in WAT and BAT depots." (PMID 26411793, 2015). "Additionally, converging with the importance of obesity as a crucial and independent risk factor for both BE and EAC development, it is largely known that HMGA1 plays a crucial role in the adipogenesis." (PMID 31737655, 2019). "In this way, HMGA1 and HMGA2 altered expression could also be envisaged as a biomarker panel to track CRC risk patients, since, under obesity condition, these genes exhibit an antagonistic expression pattern." (PMID 31737655, 2019). "Therefore, HMGA1 appears as a plausible new therapeutic target against obesity and related metabolic disorders." (PMID 26411793, 2015). "Therefore, the investigation of HMGA1 expression in obese patients could reveal important insights about EAC evolution, since obesity has been reported as an independent risk factor for EAC development, even in the absence of GERD, that is the main inductor of the BE." (PMID 31737655, 2019). "Therefore, our findings provide evidence for molecular cross-talk between HMGA1 and HIF-1, and this may be important for elucidating protein and gene networks relevant to obesity." (PMID 27445976, 2016). "However, up to now, a relationship between HMGA1 and HIF-1 has not been reported and the examination of this link could give further insights into our understanding of the regulation of genes involved in adipogenesis and obesity." (PMID 27445976, 2016).
osteosarcoma (11 papers, 2016 to 2025). A usually aggressive malignant bone-forming mesenchymal neoplasm, predominantly affecting adolescents and young adults. "Consistently, miR-142-3p has been demonstrated to function as a tumor suppressor in osteosarcoma by targeting HMGA1." (PMID 34090483, 2021). "microRNA‐758 reduces the osteosarcoma malignant phenotypes through targeting HMGA1 and Wnt signalling." (PMID 33169939, 2020). "And miRNA-142-3p has been reported could inhibit the progression of osteosarcoma cells via targeting HMGA1." (PMID 35459188, 2022). "HMGA1 was upregulated in osteosarcoma, cervical, and colorectal cancer." (PMID 34090483, 2021). "Indeed, an inverse correlation between miR-142-3p and HMGA1 expression levels was found in osteosarcoma tissues, and miR-142-3p was subsequently demonstrated to inhibit the growth, migration, and invasion of osteosarcoma cells by targeting HMGA1." (PMID 31979076, 2020). "The role of the miR-26a/HMGA1 axis in the context of cancer has been extensively studied, and this axis has been shown to act on the proliferation and migration of pancreatic cancer, bladder cancer, breast cancer, lung adenocarcinoma, and osteosarcoma cells." (PMID 31979076, 2020). "miR-26a downregulates HMGA1 by targeting its 3′-UTR, and HMGA1 knockdown significantly suppresses the migration and invasion of two osteosarcoma cell lines in vitro." (PMID 36820066, 2023). "It has been reported that miRNA-26a down-regulates HMGA1 by targeting the 3'-UTR of HMGA1 and remarkably inhibits osteosarcoma cell lines migration and invasion." (PMID 35459188, 2022). "A negative correlation between miR-26a and HMGA1 levels has also been shown in cancer tissue specimens, specifically in tissues from urothelial bladder cancer patients and osteosarcoma patients-." (PMID 31979076, 2020). "Experiments supported E2F-Sp1 interactions near: dihydrofolate reductase in Chinese hamster, dihydrofolate reductase in human osteosarcoma, fibroblast CTP:phosphocholine cytidylyltransferase in mouse embryo, thymidine kinase in mouse, RIP140 in human, CDKN2A, HMGA1, MYCN, and CDKN2C." (PMID 27871221, 2016).
pancreatic adenocarcinoma (11 papers, 2010 to 2025). "HMGA1 promotes anoikis resistance through a PI3K/Akt‐dependent mechanism in pancreatic adenocarcinoma." (PMID 36507553, 2023). "Several reports indicated that HMGA1 and HMGA2 are abundantly expressed in pancreas adenocarcinomas, where overexpression of HMGA1 correlates with advanced grade and, though less frequently, in pancreas intraepithelial neoplasias (PanIN)." (PMID 25859543, 2015). "Resistance to gemcitabine in pancreatic adenocarcinoma cells is mediated by overexpression of HMGA1 through an Akt-dependent mechanism." (PMID 25409711, 2014). "HMGA1 overexpression promotes chemoresistance to gemcitabine in pancreatic adenocarcinoma cells in vitro through an Akt-dependent mechanism." (PMID 25409711, 2014). "HMGA1 overexpression promotes chemoresistance to gemcitabine in pancreatic adenocarcinoma cells through an Akt-dependent mechanism." (PMID 25409711, 2014). "Using this model, we demonstrated that HMGA1 deficiency markedly reduced the invasive capacity of PANC-1 cells in vitro and significantly impairs tumor growth in vivo in a xenograft mouse model of pancreatic adenocarcinoma." (PMID 41145488, 2025). "To further support the association between HMGA1 and NPM1, we performed an mRNA co-expression analysis using two independently curated PDAC datasets (Pancreatic Adenocarcinoma, TCGA, GDC and Pancreatic Ductal Adenocarcinoma, CPTAC, Cell 2021) accessed through cBioPortal." (PMID 41145488, 2025). "Indeed, previous findings demonstrate that HMGA1 overexpression mediates gemcitabine resistance in pancreatic adenocarcinoma cells through an Akt-dependent mechanism, and over-activation of Akt pathway is a poor prognostic factor in cancer." (PMID 25409711, 2014). "Another promising approach for targeting HMGA1 function is the use of A/T-rich oligonucleotides in order to sequester HMGA1 and prevent target binding, which resulted in tumor size reduction in xenograft tumors originating from cultured pancreatic adenocarcinoma cells." (PMID 26117853, 2015).
pituitary tumor (11 papers, 2015 to 2022). A benign or malignant neoplasm affecting the pituitary gland. "Acting as ceRNAs, these pseudogenes elevate the expression of Hmga1 and other cancer related genes, enhancing the proliferation and migration of pituitary tumor cells." (PMID 26872371, 2016). "It has been reported that Hmga1 overexpression induces the formation of pituitary tumors in vivo." (PMID 26872371, 2016). "Moreover, a direct correlation between HMGA1 and HMGA1Ps expression in a set of human pituitary tumors, including somatotroph adenomas and NFPA or gonadotroph FSH-LH tumors has been found." (PMID 26137461, 2015).